MYB (MYB proto-oncogene, transcription factor)
Diseases named in the same sentence as MYB in open-access papers (continued):
Sharing a sentence is not in itself a finding about the gene and the disease.
tumor (continued). "The analysis encompassed the highest MYB-expressing clusters originating from epithelial, basal, and stromal lineages, with the objective of identifying a potential tumor-initiating population and tracing the lineage relationship among these cell types." (PMID 40950184, 2025). "Critically, spatial transcriptomic analyses demonstrated that plasma cells are colocalized with MYB-expressing tumor cell populations, indicative of an endogenous anti-tumor immune response." (PMID 40950184, 2025). "Our findings show that immune cell infiltration into tumor niches predominantly occurs through regions enriched with MYB-expressing structural cells." (PMID 40950184, 2025). "In renal cancer, decreased levels of MYBBP1A have been observed to increase c-MYB activity and, in response, induce the dedifferentiation of mature tumor cells into tumor stem cells." (PMID 40813991, 2025). "Rescue experiments indicated that MYB upregulation counteracted the tumor-suppressive effects of miRNA-195-5p and reactivated PI3K/AKT/mTOR signaling." (PMID 41141380, 2025). "For a definitive diagnosis, the tumor must be IDH-wild type and H3-wild type, and should exhibit a structural variant involving either the MYB or MYBL1 gene." (PMID 40861626, 2025). "By systematically investigating the active enhancer profiles of tumor samples as well as cell lines, we identified a lineage-specific super-enhancer for MYB, which contains a dominant enhancer e4 in gastrointestinal adenocarcinoma." (PMID 40234694, 2025). "Especially, MYB is a gene with an SE present in both tumor samples and cell lines of gastrointestinal adenocarcinoma (Fig. EV1B)." (PMID 40234694, 2025). "This implies a more selective recruitment of MYB to specific genomic regions under hypoxia, potentially driven by altered chromatin accessibility under hypoxic tumor microenvironment." (PMID 40680814, 2025). "In T-ALL, the transcription factors TAL1, GATA3, and RUNX1 form a positively connected self-regulatory loop that regulates T-cell homeostasis and directly activates MYB to facilitate tumor progression." (PMID 40083704, 2025). "Through a comparative analysis of the core MYB-expressing niche and adjacent non-MYB-expressing cell populations, we identified mechanistic drivers contributing to the observed tumor neoplastic cellular diversity." (PMID 40950184, 2025). "In this study, we identified a lineage-specific SE in gastrointestinal adenocarcinoma that robustly enhances the expression of MYB and controls the development of tumor." (PMID 40234694, 2025). "Overall, ERCC6L and MYB have significant biological and clinical roles in various tumors, but their expression and prognostic value differ by tumor type." (PMID 40672391, 2025). "Based on RNA-seq data of normal samples from the Genotype-Tissue Expression project (GTEx) and tumor samples from the Cancer Genome Atlas (TCGA), the expression of MYB in COAD, READ and STAD tumors was higher compared to normal tissue (Fig. EV1H)." (PMID 40234694, 2025). "These specific cell populations were prioritized based on insights from pseudotime trajectory analysis, which identified MYB-expressing epithelial cells as potential tumor-initiating clusters." (PMID 40950184, 2025). "We further found evidence of partial epithelial-mesenchymal transition (P-EMT) programming within MYB-expressing tumor clusters." (PMID 40950184, 2025). "The tumor response to hypoxia conditions is mediated by MYB and MYBL2 and their interaction with the ubiquitin ligase protein of the von Hippel-Lindau (pVHL) gene and hypoxia-inducible factors (HIFs)." (PMID 38835346, 2024). "MYB was strongly downregulated in cetuximab-resistant CRC cells, while MYB expression was associated with cetuximab sensitivity and increased tumor immune cell infiltration." (PMID 38835346, 2024). "In adenoid cystic carcinoma (ACC), tumor-promoting fusion proteins of MYB and MYBL1 with nuclear factor IB (NFIB) were identified." (PMID 38835346, 2024).
tumor (continued). "Suppression of c-MYB in rhabdomyosarcoma cells was observed to result in reduced tumour engraftment success and a slowing of tumour growth in the initial stages of tumour formation." (PMID 38995522, 2024). "In ACC — a solid tissue cancer, which, like BPDCN, shows recurrent MYB fusions — ATRA reduces MYB expression and inhibits tumor growth." (PMID 39499902, 2024). "Abnormal expression of MYB can lead to changes in immune cell infiltration in the tumor microenvironment." (PMID 39072320, 2024). "In vitro and in vivo studies have demonstrated that MYB stimulates proliferation and tumor growth and suppresses apoptosis." (PMID 38542205, 2024). "Prior functional genomics work showed that the truncated MYBL1 protein expression induced tumor formation in nude mice, supporting the notion that truncated MYB(L1) genes are a potential driver of these tumors." (PMID 39422766, 2024). "Clinical trials employing MYB inhibitors to target ACC tumor cells are underway, offering a promising direction for new drug development." (PMID 39263605, 2024). "Strong tumor growth inhibition and MYB downregulation were observed for RA in MYB-NFIB and PIK3CAR88Q mutant patient-derived ACC in combination with the PI3K inhibitor alpelisib." (PMID 38835346, 2024). "In summary, the NOTCH signaling pathway serves as a crucial differentiation signal for tumor cells, while MYB acts as a marker for undifferentiated stem cells by inhibiting differentiation programs and promoting stem cell proliferation." (PMID 39263605, 2024). "The MYC activator MYB was identified as a target of miR-103, which is a tumor suppressor downregulated in ALL." (PMID 38835346, 2024). "MYB is a direct target of ER and is required for ER+ BC cell proliferation in vitro and tumor growth in vivo." (PMID 36856111, 2023). "The function of MYB Proto-Oncogene Like 2 (MYBL2) in the tumor microenvironment remains largely unexplored." (PMID 37865750, 2023). "MYB also exhibits a positive correlation with AR expression and both display higher expression in advanced tumor stages." (PMID 38089573, 2023). "Next, we analyzed the exact immune cell infiltration in tumor immune microenvironment and found that MYB expression had a strong correlation with B cell, CD4 T cell, neutrophil and DC in most cancer types." (PMID 36994664, 2023). "To identify the potential role of MYB in tumor progression and immunity, we explored the expression of MYB in different molecular subtypes and immune subtypes in human cancers." (PMID 36994664, 2023). "ATBF1, encoded by ZFHX3, negatively regulates AFP and MYB, positively regulates CDKN1A expression, and has been reported as a tumour suppressor gene in other types of cancer." (PMID 38104198, 2023). "Further studies are needed to identify the molecular mechanisms of MYB in tumor progression and immunity." (PMID 36994664, 2023). "This alteration results in MYB protein overexpression, which has several activation mechanisms, highlighting the complexity of this tumor." (PMID 37476370, 2023). "Tumor progression can be prevented by silencing MYB, targeting the downstream effector of this gene, and blocking the protein‒protein interaction in the transcriptional complex." (PMID 37152992, 2023). "ACC is a biphasic tumour consisting of myoepithelial and epithelial cells, with MYB/MYB L1-NFIB rearrangements which occur in almost 65% of cases." (PMID 37795454, 2023). "A significantly higher expression of MYB and AR were observed in the tumor cells those were invaded into extraprostatic extension (pT3a), seminal vesicle (pT3b), or bladder and/or rectum (pT4) compared to prostate confined (pT2-pT2c) tumor." (PMID 38089573, 2023). "Considering that the relationship between immune cells and MYB expression is diverse in human cancers, we infer there is an intricate correlation between the antitumor or pro-tumor response of immune cells and MYB expression." (PMID 36994664, 2023).
tumor (continued). "A MYB breakpoint at exon 11, and another at exon 16 were detected in tumor samples HN338PT and HN344PT, respectively." (PMID 35565392, 2022). "Similar to MECa, the main genomic alteration is gene fusion (MYB-NFIB fusion is present in 29% to 86% of neoplasms)." (PMID 36146635, 2022). "Inter-Duct 3–4 cells were regulated by the TFs, MYB and EN1, and underwent activation of tumor-associated pathways." (PMID 36465348, 2022). "The mechanism behind the MYB–QKI fusion has been well studied and is proposed to be a tripartite mechanism: MYB is overexpressed, the regulatory domain of MYB is truncated and the tumor repressor function of QKI is lost." (PMID 35169893, 2022). "Positive immunostaining for MYB has been reported in several other tumours including basaloid squamous cell carcinoma, basal cell adenocarcinoma and epithelial myoepithelial carcinoma as well as HPV associated sinonasal carcinoma." (PMID 35397067, 2022). "Our results again emphasize the importance of MYB/MYBL1 gene fusions in AdCC tumor biology and their specificity to AdCC." (PMID 36077692, 2022). "And by the end of 8 weeks, tumor formation occurred with parental control (87.5 %), MYBwt (83.3%) and MYB-NFIB fusion (75%) cells." (PMID 35565392, 2022). "In a previous study, we found that 44% of tumor samples from ACC patients harbored the MYB-NFIB gene translocation." (PMID 35565392, 2022). "In vivo tumor formation analysis indicated the capacity of MYB-NFIB fusion cells to grow as implanted tumors, although there were no fusion-mediated growth advantages." (PMID 35565392, 2022). "Her tumor molecular profile performed 2.5 years after completion of treatment with BBI608 demonstrated MYB proto-oncogene (MYB) chromosomal rearrangement, BCL6 corepressor (BCOR) P698fs, and lysine demethylase 6A (KDM6A) R1415 *." (PMID 35267638, 2022). "Collectively, these results demonstrated that the BC200/miR-150-5p/MYB loop promoted the tumor growth of MDS cells in vivo." (PMID 35136029, 2022). "Further studies will be required to develop effective therapeutic interventions aiming at suppressing MYB signalling in tumours while minimising risks to patients." (PMID 33637673, 2021). "AG typically demonstrates MYB alterations with the MYB-QKI fusion being the genetic signature of this tumor." (PMID 33779771, 2021). "Many studies have confirmed that miR-150 regulates MYB and affects the proliferation of various types of tumor cells." (PMID 34876130, 2021). "The interaction between ncRNAs and MYB is involved in tumor cell proliferation, apoptosis, angiogenesis, metastasis, senescence, and drug resistance." (PMID 34876130, 2021). "Another study pointed out that MYB expression in tumor cells due to its tumorigenic role modulated the host immune response, which has the potential to influence the use of immunotherapy in CRC patients." (PMID 33515271, 2021). "This is quite interesting and suggests that MYB likely acts in concert with other molecular factors in AA OC to impact tumor biology leading to racially disparate clinical outcomes." (PMID 34145334, 2021). "In tumor cells with high MYB expression, MYB induces miR-130a expression, which inhibits the expression of tumor suppressor NDRG2 by targeting its 3'-UTR." (PMID 34876130, 2021). "ACC is commonly associated with truncation of MYB and elevated NOTCH1 expression/activity, and this patient's tumor presented with both." (PMID 33733072, 2021). "MiR-130a in GC cells is delivered into vascular cells by exosomes and directly targets c-MYB to promote angiogenesis and tumor growth in vivo and in vitro." (PMID 34195097, 2021). "There are reports that MYB mRNA expression is higher in HCC tissues than in matched non-tumor tissues, and survival analysis revealed that strong MYB expression had lower disease-specific survival rates than in patients with negative MYB expression." (PMID 34616668, 2021).
tumor (continued). "In conclusion, we found that NTT play a tumor-suppressor and tumor-promoting roles in human HCC tissues mostly from the ability to negatively or positively control MYB oncogene and suggested a context-dependent function of NTT in tumor development." (PMID 34616668, 2021). "Cancer-derived exosomes carry miR-130a from GC cells to vascular cells by targeting MYB to promote angiogenesis and tumor growth." (PMID 34876130, 2021). "Many studies have found that the interaction between MYB and ncRNAs can regulate tumor cell apoptosis." (PMID 34876130, 2021). "By analysing transcription factors (TFs) with evidence of BTLA promoter binding in ChIPseq, we found each variant tumour possessed a mutation predicted to disrupt TF binding, most frequently RUNX1/3, GATA3 and MYB." (PMID 34753926, 2021). "These promising results will serve as the basis for continued preclinical and clinical studies of ATR inhibitors in neoplasms with co-expression of MYB and ATR." (PMID 32001675, 2020). "BRAF V600E mutations were linked to GG with CD34 expression, FGFR1 mutations to DNT, MYB alterations to AG and also IDG and PRKCA fusions to PGNT, suggesting the possibility to also develop a genetically driven tumor classification scheme for LEAT." (PMID 32151273, 2020). "We chose typical cribriform AdCC as a control and found that these tumors all showed strong MYB expression in both myoepithelial and partial glandular tumor cells." (PMID 32695659, 2020). "When studying the effect of reducing the expression of MYBBP1A in vivo in xenograft models, we observed an increase in tumor size and the appearance of metastases only when injecting cells expressing c-MYB." (PMID 31968688, 2020). "Taken together, the reduction in the expression of MYBBP1A induces the activation of c-MYB, which ultimately results in an increase in the tumor stem cell phenotype." (PMID 31968688, 2020). "Preclinical studies vaccinating against the MYB proto-oncogene showed suppressed tumour growth through induction of T-cell-mediated anti-tumour immunity." (PMID 32664619, 2020). "The drug reduced Myb binding in intensifying regions in MYB-translocated patient-derived xenograft models, thereby reducing the positive feedback for Myb overexpression cycle and thus reducing tumor proliferation." (PMID 33194707, 2020). "On the other hand, the reduction in MYBBP1A levels increases tumor properties only in cell lines that express c MYB." (PMID 31968688, 2020). "As a contrast, all AdCC exhibited strong diffuse nuclear expression of MYB in myoepithelial and partial glandular tumor cells." (PMID 32695659, 2020). "On the contrary, the stronger intensity of MYB expression and higher frequency of c-Myb-positive cells were found in ER-positive tumor samples." (PMID 31406165, 2019). "In summary, our data support the role of MYBBP1A as a tumor suppressor by regulating c‐MYB and PGC1α." (PMID 31066170, 2019). "To confirm this point we have analyzed the expression of c-MYB in all tumor samples from our cohort and correlated to VHL and MYBBP1A expression." (PMID 30781655, 2019). "Our data clearly showed that MYBBP1A knock down increased the stem cell-like phenotype in some tumor cells and that these tumor cells seemed to have significant levels of c-MYB." (PMID 30781655, 2019). "Our data strongly support the role of MYBBP1A as a tumor suppressor via regulation of c‐MYB and PGC1α." (PMID 31066170, 2019). "ACCs 1–10 and ACC 22 expressed large 5′/3′ imbalances, strongly suggestive of the expression of MYB fusion transcripts in these tumours." (PMID 31301736, 2019). "Detailed analyses of MYB transcripts from ACC patient samples revealed that ACC tumors utilize an alternative MYB promoter, which is rarely used in normal cells or other tumor types." (PMID 31877778, 2019). "All remaining tumour samples including ACC 22 were shown to have comparable MYB 5′ and 3′ relative gene expression levels." (PMID 31301736, 2019).
tumor (continued). "To examine the role of MYBBP1A in human tumor progression, in relation to an increase in c‐MYB and PGC1α, we used public transcriptome databases." (PMID 31066170, 2019). "Our data support the role of MYBBP1A as a tumor suppressor by regulating stemness via repression of c-MYB." (PMID 30781655, 2019). "We found that loss of MYBBP1A release PGC1α activity and transcription activation through c‐MYB switching tumor bioenergetics, increasing glutaminolysis and sensitivity to oxidative channel inhibition." (PMID 31066170, 2019). "Our data support the role of MYBBP1A as a tumor suppressor by repressing c-MYB, acting as an important regulator of the plasticity of tumor cells." (PMID 30781655, 2019). "However, the molecular mechanism of how MYB underlies tumor progression remains unclear." (PMID 30206227, 2018). "This translocation was present in all metaphases suggesting that MYB translocation was likely to be an early event in tumor evolution." (PMID 28900283, 2017). "In accordance with previous findings, MYB mRNA was down-regulated in all our SCCT samples compared to tumor free controls adjacent to tumor." (PMID 29262574, 2017). "RNA expression of MYB was down-regulated in all SCCT samples compared to tumor free controls adjacent to tumor." (PMID 29262574, 2017). "The tumours highlighted the overexpression of MYB (fold‐change increase = ×2.04), BCL2 (fold‐change increase = ×2.34) and BIRC3 (fold‐change increase = ×3.93)." (PMID 26969893, 2016). "Ample evidence demonstrates that aberrant MYB expression is a potent driver of neoplasia in animal and human malignancies." (PMID 27533466, 2016). "We assessed MYB protein expression in inherited CYLD‐defective tumours (n = 16) to determine the frequency of MYB‐positive tumours in this group." (PMID 26969893, 2016). "This is in line with the finding of recurrent chromosomal translocations in MEC and ACC involving the MAML2 and MYB genes, respectively, which appear to play a key role in the molecular pathogenesis of these neoplasms." (PMID 26053092, 2015). "MiR-150 is a tumor suppressor gene that regulates B-cell development and NK T cell function by targeting MYB, as well as controlling the other T-cell subsets interacting with the NOTCH3 signal." (PMID 25232701, 2014). "Direct repression of MYB by the EMT driver ZEB1 builds onto the paradigm through which tumor growth, invasion, and metastasis are integrated." (PMID 24283570, 2013). "MGMT was expressed independently of ZEB1 in these tumours, supporting c-MYB as intermediate regulator of MGMT." (PMID 23818228, 2013). "Resistance to apoptosis, reduced proliferation, and tumor dormancy have all been associated with EMT in the past, but the potential role of MYB in this process is novel." (PMID 24283570, 2013). "Bas1 is homologous to the MYB TF that regulates stem and progenitor cells and appears as an oncogene in multiple tumour types." (PMID 22720667, 2012). "Notably, genes implicated in oncogenic signaling and tumor progression, including GNB4, EGF, MYB, IL6R, ANGPT4, and ITGB8, were consistently downregulated in both BxPC3 and SW1990 cells following PCDH1 silencing." (PMID 41602375, 2026). "Further studies focused on the MYB alterations may provide information about the molecular origin of the tumor and a possible marker for diagnosis." (PMID 40987753, 2026).